NLRP3 (NLR family pyrin domain containing 3)
Diseases named in the same sentence as NLRP3 in open-access papers (continued):
Sharing a sentence is not in itself a finding about the gene and the disease.
cancer (continued). "However, it remains largely unknown whether paclitaxel, a microtubule-stabilizing agent being used in cancer therapy, has any influences on NLRP3 inflammasome activation." (PMID 30761140, 2019). "To explore this mechanism in human cells, we first primed monocyte-derived macrophages from cancer-free TET2delA carriers (Ly9, Ly11, and Ly14) and controls (Ly8 and an unrelated control) with lipopolysaccharide (LPS) and interferon-γ, followed by stimulation with NLRP3 inflammasome activators." (PMID 30890702, 2019). "According to the researches, the NLRP3 inflammasome could regulate the development of the cancers." (PMID 30770793, 2019). "Consequently, the NLRP3 inflammasome can modify the malignant behaviors of cancer cells." (PMID 31492049, 2019). "The P2X7 receptor (P2X7R), trigger of the NLRP3 inflammasome, was pivotal in the cancer cell invasion associated with metastasis; thereupon by antagonizing the P2X7R specifically could inhibit the invasiveness of human cancer cell." (PMID 31412862, 2019). "Thus, we declared that the expression of NLRP3 in ccRCC cancer tissues was down-regulated and the expression of LXRα could dampen expression of the NLRP3 inflammasome in ccRCC cells." (PMID 30770793, 2019). "Therefore, inhibition of NLRP3 inflammasome activity and/or IL-1β secretion might be an approach to correct 5-FU ambivalent action in cancer patients." (PMID 31217433, 2019). "On the other hand, the NLRP3 inflammasome might suppress cancer progression." (PMID 31492049, 2019). "More recently, NLRP3 inflammasome activation has been show to activate cancer stem cells (CSCs) leading to self-renewal and acceleration of HNSCC progression, thus NLRP3 inflammasome inhibition could decrease the CSCs population in HNSCC with a consequent improvement in prognosis." (PMID 30447690, 2018). "Interestingly, NLRP3 inflammasome can be activated in a sterile setting by necrotic cancer cells." (PMID 28865486, 2017). "However, the roles of NLRP3 inflammasome in different cancers are cell- and tissue-specific." (PMID 28865486, 2017). "A study identified polyphyllin VI (PPVI) as a specific agonist that activates the ROS/NF-κB/NLRP3/GSDMD signaling pathway, effectively inhibiting NSCLC by preventing cancer cell proliferation." (PMID 39966334, 2025). "The NLRP3 inflammasome is involved in immune responses in various cancers, and numerous studies have highlighted the link between TXNIP and NLRP3 inflammasome activation." (PMID 40182050, 2025). "Notably, while the NLRP3 inflammasome was found to be responsible for IL-1β processing in pancreatic cancer cells, its expression and activation are mostly detected in tumor-associated stromal or immune cells rather than cancer cells." (PMID 39858071, 2025). "Among these inhibitors, the small molecule NLRP3 inhibitor MCC950 has shown promising results in various disease models, including autoinflammatory disorders, cardiovascular diseases, cancer, neurological diseases, and diabetes." (PMID 41560727, 2025). "Strikingly, the co-expression of NLRP3 and FLT3 is exceptionally pronounced in AML, exceeding the levels observed in all other investigated cancer types." (PMID 39875995, 2025). "Recent advances have highlighted the potential of targeting inflammasome components such as sensor proteins (e.g., NLRP3, AIM2), adaptor proteins (e.g., ASC), caspase-1, and downstream cytokines IL-1β and IL-18—to modulate the immune response against cancer." (PMID 40155968, 2025). "RNA sequencing analysis revealed that NLRP3 is a downstream regulated by SOAT1, with NLRP3 inflammasome reactivation having recovered cancer malignancy inhibited by SOAT1 knockdown." (PMID 40135589, 2025). "In summary, across cancer and fibrotic diseases, inflammasome inhibition can curb EMT by disrupting NLRP3-dependent IL1β signalling and its engagement of MAPK, NF-κB, and TGF-β/Smad pathways in order to achieve particular treatment goals." (PMID 41148809, 2025).
cancer (continued). "NLRP3—a gene from the NLR family (Pyrin Domain containing 3) which has a well-recognized role as an inducer of immunity, inflammation, and cancer development—was upregulated in our PSC-UC group." (PMID 39944929, 2025). "The role of the CRP is of significance, given that it has been identified as a potential mediator of carcinogenesis and cancer progression via the activation of the FcgRs/MAPK/ERK, FcgRs/NF-kB/NLRP3, and FcgRs/IL-6/AKT/STAT3 pathways." (PMID 40076898, 2025). "Among the various inflammasomes identified, NLRP3 and AIM2 have emerged among the most extensively characterised in cancer biology." (PMID 41148809, 2025). "While previous studies have shown the anti-inflammatory properties of morin in various diseases, our findings are the first to demonstrate its inhibitory effects on the NLRP3 inflammasome in NSCLC, highlighting its potential as a novel anti-cancer agent." (PMID 39858497, 2025). "In our study, we demonstrated the in vitro effects of morin on inflammation-related cancer metastasis in NSCLC using the A549 and H1299 cell lines primed with LPS and ATP to activate the NLRP3 inflammasome." (PMID 39858497, 2025). "By knocking down NLRP3 gene in TBM-02, we found that there is a decrease in proliferation and migration of cancer cells in comparison to wild-type cells." (PMID 41410801, 2025). "First, we compared the expression of NLRP3 (and IL‐1β and CASP‐1) in our PTCC data set with other cancer types to demonstrate that blood cancers generally express more NLRP3 (and IL‐1β and CASP‐1)." (PMID 40104043, 2025). "We evaluated the predictive performance of HYP.SIG by comparing it with established pan-cancer models for ICI response prediction, including INFG.Sig, T.cell.inflamed.Sig, PDL1.Sig, NLRP3.Sig, LRRC15.CAF.Sig, and Cytotoxic.Sig." (PMID 41419193, 2025). "RRx-001, an NLR family pyrin domain-containing 3 (NLRP3) inflammasome inhibitor and NO releaser, was found to inhibit G6PD in different cancer cells." (PMID 39061847, 2024). "Resveratrol, a natural compound, has been suggested for consideration in combination therapy as it can enhance the response of cancer cells to PARP inhibitors and reduce inflammation in the heart mediated by NLRP3." (PMID 38592677, 2024). "In a pan-cancer analysis of NLRP3 inflammasome methylation, it was found that in sporadic CRC, seven NLRP3 inflammasome-related genes (i.e., CARD8, ATAT1, CD36, NLRC3, NLRP3, PSTPIP1, and TXNIP) showed altered DNA methylation statuses." (PMID 38892354, 2024). "In this review, we discuss about various small molecule modulators of targets such as STING/ENPP1, TLR, NLRP3, and SIRPα-CD47 which are key players in the innate immune system working against cancer." (PMID 39318624, 2024). "The NLRP3 inflammasome consists of the adaptor and effector proteins NLRP3, Caspase-1, and ASC, which are abundantly produced by cancer cells." (PMID 38904007, 2024). "Thus, the NLRP3 inflammasome may have a bifunctional effect in cancer." (PMID 39144184, 2024). "The interaction between NLRP3 inflammasomes, inflammatory cytokines like IL-18 and IL-1b, and TNBC has been found to promote cancer development with the potential for novel anti-inflammasome treatments in this type of cancer." (PMID 39409110, 2024). "In cancer cells, HIF-1α expression is related to the NLRP3 inflammasome, the Warburg effect, and EMT/metastasis." (PMID 38904007, 2024). "The specific NLRP3 antagonist MCC950 can repress the activation of NLRP3 inflammasomes, which can cut down the vitality of cancer cells." (PMID 38182564, 2024). "Intriguingly, NLRP3 and FBXW7 are consistently identified as miR-223 targets when the miRNA acts as an oncosuppressor or an oncogene, respectively, in different cancers." (PMID 39125761, 2024). "NLRP3, NOD2, and NLRP1 were all highly expressed in primary tumors, further validating the protective role of PRGs in inhibiting cancer metastasis." (PMID 38697992, 2024).
cancer (continued). "In cancer‐induced bone pain model, NLRP3 inflammasome inhibitor MCC950 treatment restores the expression of NLRP3 inflammasome and significantly suppresses the upregulation of IL‐1β, attenuates mechanical allodynia." (PMID 38334255, 2024). "We showed that cancer-derived exosomal Alu RNA can be delivered to CRC cells and promote cancer progression by inducing EMT through NLRP3 inflammasome activation." (PMID 38486106, 2024). "NLRP1, NLRP3, NLRC4, NLRP6, and AIM2 have been demonstrated to influence the pathogenesis of cancer by modulating innate and adaptive immune responses, cell death, and proliferation." (PMID 39684769, 2024). "Mechanistically, mefenamic acid is a known inhibitor of the pro-inflammatory NLRP3 inflammasome, which is suggested to be at least partially responsible for the elevated NLR that we see reported across cancer types." (PMID 36980755, 2023). "Albeit the mechanistic link with NLRP3 pathway is still missing, by inhibiting cytoskeletal protein LASP1 and PDLIM1, Oridonin induces apoptosis of EC cells, thus arresting cancer growth." (PMID 37891577, 2023). "Post-anti-cancer therapies, dying cancer cells release ATP and activate P2X7R in DCs, leading to IL-1β secretion via P2X7R-dependent NLRP-3 inflammasome assembly, and this suggests the role of NLRP-3 inflammasome in the efficacy of anti-cancer therapies." (PMID 36741002, 2023). "Hence, NLRP3 could be a promising new candidate of cancer targeted therapy." (PMID 38026959, 2023). "In total, 14 DECRs were identified, of which six regulators (MTF1, DLST, NLRP3, DBT, FDX1, and DLD) were downregulated in cancer tissues." (PMID 36672336, 2023). "In consideration of multiple function of NLRP3 inflammasome, the role of UGRP1 should also be investigated extensively in lung inflammation, injury and cancer." (PMID 35652821, 2022). "Lessons from NLRP3/IL-1ß and CD20 cells in cancer and CVD indicate their complexity in the pathogenesis of both separate disease entities." (PMID 36466820, 2022). "However, the effect of azithromycin on NLRP3 in cancer cells remain unknown." (PMID 36012769, 2022). "Among the cancers analyzed, the correlations between NFE2L3 and NLRP3 are also statistically significant, among which the correlation is relatively low in LUSC (Cor = 0.158), and the correlation is highest in DLBC (Cor = 0.638)." (PMID 35664314, 2022). "The expression of selected 6 PRGs (GSDMC, GSDMD, GSDME, NLRP3, NLRC4, and IL1B) was assessed in 6 types of cancers and adjacent normal tissues." (PMID 36605187, 2022). "Compared with pan-cancer signatures (INFG.Sig, T.cell.inflamed.Sig, PDL1.Sig, LRRC15.CAF.Sig, NLRP3.Sig, and Cytotoxic.Sig), Stem.Sig showed best performance in the testing set with an AUC of 0.71, followed by INFG.Sig with an AUC of 0.66." (PMID 35488273, 2022). "As examples MCC950 and OLT1177, block NLRP3 oligomerization by inhibiting ATP hydrolysis via the NACHT domain, which is pivotal for receptor oligomerization and anti-cancer effects." (PMID 35530309, 2022). "It is the contention of this paper on TICO that, based on data reviewed above, the activated NLRP3 inflammasome, MDSC, G(M)-CSF form a constellation, a triad that is at least partially responsible for the elevated NLR and NETs that we see in cancer." (PMID 36230888, 2022). "RRx-001, an anti-cancer agent in phase III clinical trials, is currently identified as a highly selective NLRP3 inhibitor that covalently binds to cysteine 409 of NLRP3 and, therefore, blocks the assembly of the inflammasome." (PMID 35883561, 2022). "In contrast to other CGRs, ATP7B, NLRP3, and ATP7A were distinctly hypomethylated in multiple cancers, such as BRCA, LUSC, and LUAD." (PMID 36387247, 2022). "In summary, metastasis of cancer cells in bone activates GSK‐3β/Drp1 pathway, resulting in mitochondrial fission and dysfunction, activating NLRP3 inflammasome and consequently inducing nociceptive response." (PMID 35689386, 2022).
cancer (continued). "In conclusion, for the first time, we analyzed the effect of the macrolide Az and lactamide Cf antibiotics on NLRP3 activation in A549 and PC3 cancer cells." (PMID 36012769, 2022). "Overall, the NLRP3, PJVK, TIRAP, IL18, NLRP1 and NLRP6 genes were thought to protect against cancer, while the rest of the pyroptosis genes seemed to be correlated with cancer risk." (PMID 35246158, 2022). "The results showed that compared with normal cells (N), the NLRP3, EDN1, HMOX1, and CXCL1 genes were upregulated in the cancer cell group (T)." (PMID 36118079, 2022). "NLRP3 inflammasome activation is related to nuclear factor-kB (NF-kB) activation by TLR signaling and is a key link between inflammation and cancer." (PMID 34540671, 2021). "When cancer cells were co-cultured with TAM, we found that the expression of NLRP3, AIM2, cleaved-caspase 1, and IL-1β was significantly upregulated." (PMID 34815793, 2021). "Intriguingly, the NLRP3 inflammasome can also control platelet activation, a key feature in PDA, by promoting platelet aggregation and cancer progression and interfering with patient survival." (PMID 34064909, 2021). "However, the effect of doxycycline on NLRP3 in cancer cells remains unknown." (PMID 34577552, 2021). "Inflammasome NLRP3, NLRP1, NLRC4, and AIM2 play a role in cancer pathogenesis by human immunity and programmed cell death regulation." (PMID 34753832, 2021). "NLRP3 inflammasomes, therefore, leads to multiple faces of MDS pathogenesis—ineffective hematopoiesis, cytopenias, and β-catenin induced proliferation of cancer cells." (PMID 34521810, 2021). "However, excessive and aberrant NLRP3 inflammasome activation may lead to cancer progression." (PMID 34681768, 2021). "It is widely accepted that the expression level of NLRP3 and AIM2 can predict the inflammasome signaling activity in cancers." (PMID 34815793, 2021). "Of these, NLRP1, NLRP3, NLRC4, NLRP6, and AIM2 influence the pathogenesis of cancer using various mechanisms of action." (PMID 33614494, 2020). "NLRP1, NLRP3, NLRC4, NLRP6, NLRP7, and NLRP12 have mixed roles in the pathogenesis of a variety of cancers as reviewed here in details." (PMID 33584697, 2020). "NLRP3 stimulates the enrolment of myeloid cells into the TME, especially of MDSC and TAMs, thereby enhancing cancer development." (PMID 33014808, 2020). "In this review, we discuss the crosstalk between oncogenic KRAS, inflammation and immune-modulatory mechanisms in cancer, with a focus on KRAS-induced NLRP3 inflammasome activation and programmed death-ligand-1 (PD-L1) expression." (PMID 33116132, 2020). "In an inflammation-driven cancer setting, we previously reported that myeloid S1PR1 signaling induces IL-1β production by enhancing NLRP3 (NOD-, LRR- and Pyrin Domain-Containing Protein 3) inflammasome activity." (PMID 32630814, 2020). "The NLR family (NLRP1, NLRP3, NLRC4, NLRP6, and NLRP12) and their binding partners have mixed roles in the pathogenesis of a variety of cancers." (PMID 33584697, 2020). "NLRP3 and IL1B were upregulated in cancer tissue compared to normal, while IL6 expression was unaltered." (PMID 32630814, 2020). "Specifically, overexpression of LncRNA ADAMTS9 promoted LDH release, and increased NLRP3 and ASC expression levels in cancer tissues, and promoted IL-18 and IL-1β expressions in mice serum." (PMID 32516127, 2020). "Then, PKR becomes activated and allows NLRP3 inflammasome assembly with ASC and caspase-1 activation in cancer cells." (PMID 33261061, 2020). "In cancer cells, TAT-FADD suppresses the canonical NLRP3 inflammasome priming and restricts the processing and secretion of proinflammatory IL-1β." (PMID 32961826, 2020). "We also analyzed the relationship between NLRP3 inflammasome expression levels and LSCC cancer tissues compared with adjacent normal tissues and the clinical features of LSCC." (PMID 31312615, 2019).
cancer (continued). "In a transgenic mouse model of inflammation-driven cancer, we have previously shown that macrophage S1PR1 signaling is crucial for lymphangiogenesis by activating the NLRP3 inflammasome and subsequent activation of IL-1β release." (PMID 31357710, 2019). "Several inflammasomes including NLRP3, NLRP1, NLRC4, pyrin and AIM2 play a vital role in cancer pathogenesis through their regulation of immunity and apoptosis." (PMID 31492049, 2019). "In this line, NLRP3 inflammasome plays an important role in UVB-induced skin inflammatory responses and has a critical function in skin pathologies initiation such as cancer." (PMID 31374828, 2019). "Our results were consistent with these studies, but the novel finding in our study was that the expression of NLRP3 significantly upregulated in SCCHN tissues and cancer cell lines." (PMID 28865486, 2017). "Considering that the TGF- β1 promotes cancer invasion and metastasis via enhancement of EMT related genes, it is possible that this mechanism is behind reduced invasion by P2X7R and NLRP3 inhibition." (PMID 28430665, 2017). "In addition, the role of NLRP3 in cancer development might be tissue or cell dependent." (PMID 27206676, 2016). "Nonetheless, we provide strong evidence that the chemoradiotherapeutic activation of the NLRP3 and AIM2 inflammasomes, via cathepsin B and ROS, is likely to emerge as a crucial player in the regulation of cancer immunotherapy." (PMID 23065753, 2012). "In order to delineate the function of inflammasomes in other cancer types, we evaluated the expression patterns of AIM2, RIG-I, NLRP3, ASC and caspase-1 in 114 cancer cell lines involving 22 cancer types." (PMID 23065753, 2012). "The regulation of HTR2B in NLRP3 inflammasome pathway in cancer has not been reported in previous studies." (PMID 40387572, 2025). "When we reactivated the NLRP3 inflammasome in OSCC cells, the malignancy inhibited by SOAT1 knockdown was recovered, confirming that NLRP3 inflammasome as the downstream of SOAT1 play a vicious role for cancer progression." (PMID 40135589, 2025). "Therefore, this review will primarily focus on NLRP3 and AIM2 inflammasomes in the context of cancer-related EMT and its therapeutic modulation." (PMID 41148809, 2025). "Active NLRP3 inflammasome signaling and IL-1β secretion have been observed in GBM, and NLRP3-driven myeloid-derived suppressor cell (MDSC) recruitment can mediate cancer immune evasion." (PMID 40377974, 2025). "The possible apoptotic pathways for anti-cancer effects of curcumin on cell signal transduction include PI3K, Akt, mTOR, ERK5, AP-1, TGF-β, Wnt, β-catenin, Shh, PAK1, Rac1, STAT3, PPARγ, EBPα, NLRP3 inflammasome, p38MAPK, Nrf2, Notch-1, AMPK, TLR-4, and MyD-88." (PMID 41149437, 2025). "Other genes, such as NLRP3, BCL2, and TIM4, are also affected by MPs in the mentioned cancer." (PMID 41378310, 2025). "First, we interrogated the expression of NLRP3, CASP1, and IL‐1β in 90 pediatric ALL PDX samples (Pediatric Preclinical Testing Consortium [PPTC] data set) that served as a platform for choosing the most suitable PDX model to study MCC950 effects on cancer." (PMID 40104043, 2025). "In addition, co-expression analysis using the TCGA Pan-Cancer dataset via UCSC Xena revealed a positive correlation between NLRP3 and FLT3 in more than 30 different cancer types." (PMID 39875995, 2025). "A recent preclinical study suggested that GLP-1 RA might have anti-cancer properties, reducing cancer cell growth and inflammation in vitro through AMPK/mTOR and NLRP-3 pathways." (PMID 39457081, 2024). "Finally, 379 cancer samples from TCGA and UCSC were used to extract 76 necroptosis-related genes, including NLRP3, TLR4, and IRF6." (PMID 38750159, 2024). "Comparing the response groups, the proportions of Macro_NLRP3 and Mono_CD14 significantly increased in the R group across many cancer types, whereas no obvious proportional changes were observed in the NR group." (PMID 39034339, 2024).